MTOR (mechanistic target of rapamycin kinase)
Diseases named in the same sentence as MTOR in open-access papers (continued):
Sharing a sentence is not in itself a finding about the gene and the disease.
colon carcinoma (continued). "Moreover, the angiogenesis inhibition of cryptotanshinone (CPT) was implicated in multi-signaling, including Wnt/β-catenin/VEGF axis, VEGFR2 and its downstream Src/FAK, ERK1/2 in HUVECs, while it leads to the downregulation of PI3K/Akt/mTOR signaling and HIF-1α in CT26 colon cancer cells." (PMID 35784750, 2022). "PI3K-Akt-mTOR signaling pathway is one of two downstream signaling pathways of EGFR, which can promote colon cancer cell proliferation, prolong cell survival, inhibit cell apoptosis, and participate in angiogenesis, leading to invasion and metastasis of colon cancer." (PMID 34765011, 2021). "These transcriptional signatures are mainly involved in immune regulation (CEBPB, STAT3, and JAK2), metabolism (PPARGC1 and MTOR), cell cycle (CDK1), and apoptosis (BCL2), suggesting that the deregulation of these pathways in CTS may contribute to the altered prognosis in colon cancer." (PMID 31186640, 2019). "In addition, silencing of sodium pump dramatically inhibited both PI3K and Akt but not mTOR in human colon cancer cells." (PMID 29568394, 2018). "Indeed, isogenic HCT116-human colon cancer cells expressing wild-type (HCT116 MW) and rapamycin-resistant S2035I mutants of MTOR (HCT116 MM) showed a similar sensitivity to the leucine signaling inhibitor, whereas HCT116 MM cells showed a reduced sensitivity to rapamycin." (PMID 28963468, 2017). "Our findings suggest that BRAF600E and some KRAS mutant colon cancers are unlikely to respond to mono therapy targeting mTOR, but might benefit from combination therapy with BH3 mimetics, or inhibitors of PI3K, Raf or MEK." (PMID 27351224, 2016). "HGUE-C-1 represents a novel and peculiar colon carcinoma model to study chemoresistance to chemotherapeutic agents and to novel anti-neoplasic drugs that interrupt signalling pathways such as the APC/βcatenin, Ras/Raf/Mek/Erk, PI3K/mTOR/p70S6K pathways as well as histone regulation mechanisms." (PMID 25885658, 2015). "In conclusion, the present study indicated that mTOR and pmTOR were significantly expressed in patients with stage IIIB colon cancer, and a high expression of pmTOR was detected in the forefront of tumor-infiltrating cells, increasing the mortality rate of colon cancer patients." (PMID 25120661, 2014). "We hypothesize that hyperactivation of the mTOR pathway may only affect proliferation and angiogenesis during the advanced stages of colon cancer; however, it may not affect patient survival, as a result of present comprehensive intervention treatment methods." (PMID 25120661, 2014). "It is worth noting that AZD8055, as an mTOR inhibitor, has shown anti-tumor potential by inhibiting mTORC1 and mTORC2, and its application research involves a variety of cancers such as bladder cancer, colon cancer and cervical cancer, but has not yet involved OSCC." (PMID 41286896, 2025). "In addition, FTGs activated the AMPK/mTOR autophagy pathway and downregulated the expression of JAK2/STAT3 apoptotic pathway proteins, while upregulated the expression of Bax and caspase-3 proteins and downregulated the expression of Bcl-2 proteins to exert an anti-colon cancer role." (PMID 38202610, 2023). "Therefore, our finding of matrine’s inhibitory effect on colon cancer cell growth may be independent of the PI3K/AKT/mTOR pathway." (PMID 31849679, 2019). "In summary, these results indicate B220 combined with the induction of autophagy using the dual PI3K/mTOR inhibitor, NVP-BEZ235, might be an attractive strategy for cancer therapy, and provides a framework for further development of B220 as a new therapeutic agent for colon cancer treatment." (PMID 28963527, 2017). "In vitro colon cancer assays demonstrated that FGFR2 signaling promotes PD-L1 expression through the JAK/STAT signaling pathway and is not affected by mammalian target of rapamycin (mTOR) or MAPK signaling." (PMID 36966334, 2023).
colon carcinoma (continued). "C26 CM upregulated Ddit4, Akt1, and mTOR expression and downregulated phospho-4E-BP1, and phospho-p70S6K in C2C12 compared with CM of CT26, another colon cancer cell line that could not lead to cancer cachexia." (PMID 34175899, 2021). "Among the upstream regulators (TFs, kinases, and MMTRs) of the DEGs, the expression of STAT3, RPS6KA5, IKBKE, ERBB2, MTOR, and NFKB1 had a positive correlation with OS in colon cancer, while the expression of CDK1, CDK5, and BRD2 had a negative correlation with OS in colon cancer." (PMID 31186640, 2019).
renal cell carcinoma (388 papers, 2007 to 2026). "The mTOR pathways are commonly dysregulated in cancer, but activating mutations in MTOR are rarely observed outside of renal cell carcinomas." (PMID 39271965, 2024). "Our results discovered that high METTL14 expression had association with ERBB pathway, MAPK pathway, mTOR pathway, renal cell carcinoma, TGF-β pathway and Wnt pathway by GSEA." (PMID 33430867, 2021). "This molecular rationale justified the use of the inhibition of mTOR but further studies are needed to determine if this group of therapies provides benefit in patients with BHD-associated renal cell carcinoma." (PMID 34207825, 2021). "The results revealed that low expression of IL20RB was closely associated with Wnt, mTOR signaling pathway, fatty acid metabolism, and renal cell carcinoma." (PMID 32315986, 2020). "Many types of cancer show mutations along the PI3K/AKT/mTor pathway including neuroendocrine tumors, renal cell carcinoma, breast cancer, perivascular epithelioid cell tumors, and gastrointestinal stromal tumors." (PMID 31781977, 2019). "mTOR inhibitors have been shown to reduce the incidence of malignancies and possibly cause regression of renal cell carcinoma, skin cancers, and Kaposi's sarcoma in transplant patients." (PMID 27195169, 2016). "A point mutation in mTOR, R2505P, has been identified in renal cell carcinoma, and confers constitutive activation of mTOR signalling." (PMID 22738081, 2011). "In contrast, when assessing the associations of the mTOR pathway inhibitor temsirolimus, the strongest association is with its licensed indication in renal cell carcinoma." (PMID 20011464, 2009). "Recently, it was proposed that renal CSCs isolated from renal cell carcinomas can mediate tumor growth and be the cause for resistance to standard chemo- and radiotherapies, and even tyrosine kinase receptor inhibitors, mTOR inhibitors, VEGF antibodies, cytokines, checkpoint inhibitors, etc.." (PMID 36077742, 2022). "Notably, enrichment analysis showed that overexpression of NUPR1 was associated with the cancer pathway, cancer cell stemness, mTOR pathway and renal cell carcinoma." (PMID 34030133, 2021). "Autophagy-related and cancer-related pathways were mainly enriched in low-risk patients, including regulation of autophagy, mTOR signaling pathway, renal cell carcinoma, pathways in cancer, and MAPK signaling pathway, indicating that the autophagy was mainly involved in patients with low-risk ccRCC." (PMID 33869028, 2021). "Similarly, the METTL3 expression level is associated PI3K/AKT/mTOR pathway molecule expression levels and is related to unfavorable outcomes in renal cell carcinoma." (PMID 34248650, 2021). "Furthermore, in renal cell carcinoma, the efficacy of the mTOR inhibitor temsirolimus was associated with increases in serum cholesterol levels after treatment." (PMID 29731968, 2018). "There was also one report that an SNP (rs2295080 G > T) in the promoter region of MTOR gene could affect individual susceptibility to renal cell cancer by modulating the endogenous MTOR expression level." (PMID 27270650, 2016). "Interestingly, we found a prominent cluster of hyperactivating mutations in the FAT (FRAP-ATM-TTRAP) domain of mTOR in renal cell carcinoma that led to an increase in both mTORC1 and mTORC2 activities and led to an increased proliferation of cells." (PMID 26255626, 2015). "mTOR is strongly associated with proliferation and cell survival, and mTOR inhibitors have been used in clinical applications as a molecular target drug against malignant tumors, such as renal cell carcinomas." (PMID 25887043, 2015). "In the Phase III Advanced Renal Cell Carcinoma (ARCC) trial, high-risk RCC patients with various histological types were randomized to receive IFNα or mTOR inhibitor temsirolimus." (PMID 36359359, 2022). "Deficiency of tumor suppressor FLCN leads to the activation of the mTOR signaling pathway in human BHD-associated renal cell carcinomas (RCC)." (PMID 26418749, 2015).
renal cell carcinoma (continued). "Recent studies have shown that DEPDC1 regulates glycolysis in renal cell carcinoma through the AKT/mTOR/HIF1α pathway." (PMID 40722708, 2025). "In renal cell carcinoma, a second-generation MTOR inhibitor, MLN0128, was used to treat realistic patient-derived tissue slice grafts and showed decreased levels of 4EBP1, c-Myc, and p-S6K1." (PMID 40564038, 2025). "This led rapamycin and related mTOR inhibitors (like everolimus and temsirolimus) to be repurposed for cancer therapy, particularly where mTOR is highly active, such as renal cell carcinoma and certain types of breast and neuroendocrine tumours." (PMID 40652143, 2025). "For example, in renal cell carcinoma, machine learning can analyze transcriptomic data alongside genomic and metabolic resistance markers like mTOR and mitochondrial DNA alterations." (PMID 41182434, 2025). "CXCL13 has been shown to activate mTOR signaling pathway through its interaction with CXCR5 on renal cell carcinoma." (PMID 40599793, 2025). "Male hub genes were uniquely enriched in the “FoxO signaling pathway,” “HIF-1 signaling pathway,” “mTOR signaling pathway,” “Renal cell carcinoma” and “Chemokine signaling pathway,” all of which are crucial in tumorigenesis." (PMID 40458476, 2025). "mTOR inhibitors target the mammalian target of rapamycin and are utilized in the treatment of renal cell carcinoma (RCC), as well as for their immunosuppressive properties to prevent graft-versus-host disease following transplantation." (PMID 40227621, 2025). "The mTOR inhibitor everolimus has been approved as a sequential or second‐line therapy for renal cell carcinoma (RCC)." (PMID 39119834, 2024). "The overexpression of POSTN has also been verified to promote EMT in renal cell carcinoma cells by activating the IKL/AKT/mTOR pathway." (PMID 38280891, 2024). "For example, temsirolimus is an mTOR inhibitor, which is approved for treating renal cell carcinoma and is in the clinical trials phase for HNSCC." (PMID 37488620, 2023). "In renal cell carcinoma, the PI3k/Akt/mTOR axis was confirmed to promote the aggressiveness of tumor and poor prognosis of patients via various mechanisms." (PMID 38093375, 2023). "The rapamycin analogs, which inhibit mTOR, have been approved for treating renal cell carcinoma, while several other mTOR inhibitors are currently in development." (PMID 37649478, 2023). "Temsirolimus is an anti-cancer agent used for the treatment of advanced renal cell cancer and is an inhibitor of the mammalian target of rapamycin (mTOR)." (PMID 37180434, 2023). "Recently, researchers demonstrated that CEP55 promoted the epithelial-mesenchymal transition (EMT) and activated the PI3K/AKT/mTOR pathway in renal cell cancer." (PMID 37484531, 2023). "KEGG pathway analysis revealed that the main pathways included “Rap1 signaling pathway”, “Renal cell carcinoma” and the “mTOR signaling pathway”." (PMID 35449001, 2022). "The introduction of tyrosine kinase inhibitors (TKI) and mTOR targeted therapies in combination with immunotherapies has been a major step forward in the treatment of renal cell carcinoma." (PMID 35563753, 2022). "Temsirolimus, another mTOR inhibitor similar to everolimus, was approved as an advanced renal cell carcinoma therapeutic by the FDA in 2007." (PMID 35216405, 2022). "Everolimus is an mTOR inhibitor that was first approved for use in treating advanced renal cell carcinoma in 2009 and for preventing kidney transplant rejection in 2010." (PMID 35216405, 2022). "The US Food and Drug Administration (FDA) approved an mTOR inhibitor for the treatment of renal cell carcinoma, named temsirolimus." (PMID 35558559, 2022).
renal cell carcinoma (continued). "We have demonstrated the efficacy of gypenosides in inducing apoptosis of renal cell carcinoma via activation of the PI3K/AKT/mTOR pathway." (PMID 35370678, 2022). "Increasing researchers have shown that mTOR plays a crucial role in the development of renal cell carcinoma, and CTSK is closely related to the mTOR signaling pathway." (PMID 36005209, 2022). "The efficacy and safety of mTOR inhibitors has been demonstrated in different tumors, including lymphomas, breast and renal cell carcinomas (RCC)." (PMID 33916707, 2021). "Everolimus, at type of mammalian target of rapamycin (mTOR) inhibitor, is approved for the treatment of advanced renal cell carcinoma, metastatic hormone receptor-positive breast cancer, and pancreatic neuroendocrine tumors (P-NETs)." (PMID 33868173, 2021). "GNE-477, a novel dual inhibitor of PI3K/mTOR, has been demonstrated to inhibit the growth of renal cell carcinoma cells in vitro and in vivo." (PMID 34381355, 2021). "Genes in Cluster 1 were enriched for various functions related to cancer development, such as the TGFβ signaling pathway, renal cell carcinoma, and mTOR signaling pathway." (PMID 34646862, 2021). "8-chloroadenosine has also been shown to cause inhibition of mTOR and activation of AMPK in renal cell carcinoma cell lines." (PMID 35586115, 2021). "Deleted genes in the ES group were enriched in “basal cell carcinoma”, “proteoglycans in cancer”, “biosynthesis of amino acids”, “renal cell carcinoma” and “mTOR signaling pathway”." (PMID 34745971, 2021). "MAGEA6 silencing was found to inhibit human colorectal and renal cell carcinoma and prevented mTOR signaling." (PMID 34943938, 2021). "The results showed that pathways involved in propanoate metabolism, mTOR signaling pathway, cell adhesion, cytokine receptor interaction, and renal cell carcinoma were significantly different." (PMID 34512796, 2021). "The induction of mTOR by FOXO3 stimulates activation of AKT in renal cell carcinoma, while inhibition of FOXO3 activity enhances the sensitivity of renal cell carcinoma cells to PI3K and AKT inhibitors." (PMID 34123834, 2021). "In renal cell carcinoma, the expression of mTOR is higher than that in the normal renal tissues and is therefore acclaimed as a target in the treatment of RCC." (PMID 33959154, 2021). "Targeted therapies (e.g., vascular endothelial growth factor receptor [VEGFR] tyrosine kinase inhibitors [TKIs] and mammalian target of rapamycin [mTOR] inhibitors) have been the standard of care for renal cell carcinoma (RCC) since 2008 in Japan." (PMID 34291367, 2021). "Several elements highlight the importance of the mechanistic target of rapamycin (mTOR) in the biology of renal cell carcinoma (RCC)." (PMID 33791295, 2021). "CC-115 is a dual inhibitor of DNA-PKcs and mTOR, both are valuable therapeutic targets for renal cell carcinoma (RCC)." (PMID 33109772, 2020). "Sustained activation of PI3K-Akt-mTOR cascade is important for renal cell carcinoma (RCC) cell progression." (PMID 32421688, 2020). "TH-302 has already been shown to improve mTOR-targeted therapies in renal cell carcinoma, and within our models, AZD2014 alone has demonstrated a clear survival benefit, equivalent to that of gemcitabine." (PMID 29898401, 2018). "The mechanistic target of the rapamycin (mTOR) inhibitor, temsirolimus, has significantly improved the outcome of patients with renal cell carcinoma (RCC)." (PMID 29721158, 2018). "These discoveries led to the evaluation of temsirolimus and everolimus, which are both mTOR inhibitors in the management of renal cell carcinoma." (PMID 30513765, 2018). "In the METEOR trial, 658 patients with advanced renal cell carcinoma who progressed with at least one VEGFR small molecule inhibitor were randomized to the MET inhibitor cabozantinib or the mTOR inhibitor everolimus." (PMID 29866143, 2018).